MTOR (mechanistic target of rapamycin kinase)
Diseases named in the same sentence as MTOR in open-access papers (continued):
Sharing a sentence is not in itself a finding about the gene and the disease.
cancer (continued). "Notably, ca-S6K1 alone also promoted proliferation of above cancer cells, further confirming the positive role of mTOR in promoting cell proliferation." (PMID 27894091, 2017). "Various cancers have been associated with impaired AMPK activation and/or mTOR inhibition." (PMID 28808653, 2017). "Based on our results, the overexpression of downstream proteins in protein synthesis-related pathways, such as EIF3D, may be contributing to the acquired resistance of cancer cells to mTOR inhibition, a hypothesis meriting further investigation." (PMID 29050215, 2017). "mTOR is an attractive target for cancer therapeutic intervention." (PMID 29137365, 2017). "Use of mTOR inhibitors together with calcineurin inhibitor minimization offer a reasonable option in kidney transplant recipients who developed post-transplant cancers in view of stable renal function, low rejection rate and low cancer recurrence rate." (PMID 28160552, 2017). "Indeed, both the mTOR and MAPK pathways are well known to be involved in several cancers via coding mutation." (PMID 28333948, 2017). "Importantly, CD133 can interact with p85 to activate PI3K/AKT/mTOR-signaling pathways in cancer stem cells, and this activation consequently provokes cancer stem cells to promote tumorigenic capacity." (PMID 28687090, 2017). "Moreover, it has been found that TQ can directly modulate the activation of several signal transduction pathways including PI3K-Akt-mTOR that are frequently upregulated in various cancers and confer resistance to radiotherapy." (PMID 28659794, 2017). "Modulating the AMPK/mTOR pathway with phytochemical compounds could be one useful strategy for cancer prevention and control." (PMID 28146060, 2017). "AKT/mTOR is an attractive target for the development of novel inhibitors that might prove beneficial in the treatment of cancers in which this pathway is constitutively activated." (PMID 28972559, 2017). "Therefore, dual inhibition of PI3K/Akt and mTOR is an effective strategy for targeting cancer cells." (PMID 28785288, 2017). "Mammalian target of rapamycin (mTOR), an evolutionarily conserved and ubiquitous serine/threonine kinase, plays a central role in regulating cell proliferation, apoptosis, autophagy and migration, being considered a hotspot target for cancer therapy." (PMID 28455969, 2017). "In addition, another study also showed that eGFR improvement was less among patients who had mTOR inhibitor conversion due to cancers when compared with those who had conversion due to chronic graft dysfunction." (PMID 28160552, 2017). "Further studies will improve our understanding of how ATRX and ERBB4 mutations and AKT/mTOR signaling promote CSCNET tumorigenesis, and may be leveraged in novel anti-cancer treatment strategies." (PMID 28042953, 2017). "Furthermore, PI3K/Akt/mTOR is one of the most frequently altered signaling pathway known to play an important role in glycolysis, cancer metabolism and cancer cell proliferation." (PMID 28348562, 2017). "The survival pathway of Akt, its downstream effectors, the mammalian target of rapamycin (mTOR) and ribosomal protein S6 kinase (p70 S6K), and the Ras-extracellular signal-regulated kinase (Erk1/2) pathways are activated in cancer leading to cell survival and growth." (PMID 28481292, 2017).
cancer (continued). "Second generation active site directed mTOR inhibitors, that target both mTORC1 and mTORC2, demonstrate significantly improved anti-cancer activity in preclinical models when compared with rapalogues; a variety of these mTOR inhibitors are now being explored in the clinic with mixed results." (PMID 29156676, 2017). "The Ras/Raf/MEK/ERK and PI3K/Akt/mTOR signaling pathways are essential for cancer cell survival." (PMID 29259156, 2017). "Biologically, these correlations are related to the mitogen activity of these molecules on cancer cells because, through one transmembrane-segment receptors (1STMR), they stimulate mTOR activation that is a common therapeutic target of several cancer the prostate one." (PMID 28389628, 2017). "EMT progression was also suppressed by β-lap, and these anti-cancer effects may be due to Akt/mTOR pathway inactivation." (PMID 28578385, 2017). "It was also found that CONPs could decrease the expression of p-AKT, p-mTOR, and increase the expression of 4EBP1, which are crucial in the development of cancer." (PMID 28977848, 2017). "The results lead to a model about the functionality of self‐sustaining cancer cells using PDK‐RSK survival pathway in combination with the SRC‐dependent proliferation pathway to finally benefit from the synergy effect of mTOR activation being responsible for drug resistance." (PMID 28675785, 2017). "Recent studies indicate that combined PI3K/mTOR inhibitor with HDAC inhibitor may be more efficacious than single drug in some cancer cells." (PMID 28060760, 2017). "To date, sufficient evidence has been accumulated to support that phenolic compounds of Olea europaea might be able to activate AMPK pathways in cancer cell lines through the AMPK/mTOR axis." (PMID 28278224, 2017). "Rapamycin, different from other therapeutic agents, has been proven to induce autophagy via mTOR inhibition in cancer cells; nevertheless, it also has been considered as an immunosuppressive drug because of its ability to impair DC maturation and T cell proliferation." (PMID 28629173, 2017). "Several therapeutic agents, such as tyrosine kinase and mTOR inhibitors as well as immunotherapeutics (sunitinib or sorafenib), have demonstrated significant improvements regarding response rates, cancer-specific progression-free survival rates, and overall survival rates of advanced RCC patients." (PMID 29165391, 2017). "Lung and breast cancers are two major cancers with frequent PI3K-Akt-mTOR pathway alterations." (PMID 29152062, 2017). "p-mTOR expression showed tissue and cell type specificity in normal and cancer tissues." (PMID 28831205, 2017). "In a broader scope beyond sunitinib, accumulating evidence reported compensatory activation of PI3K/AKT/mTOR signaling pathway and/or heightened Mcl-1 expression in diverse cancer types resistant to other TKIs including imatinib, dasatinib, erlotinib, and gefitinib." (PMID 29066973, 2017). "Thus, targeting the mTOR pathway is considered to be a valid therapeutic approach for cancer treatment." (PMID 29088718, 2017). "Metabolic reprogramming is crucial for tumor progression to foster cancer cells growth and proliferation, and is regulated by mechanistic target of rapamycin (mTOR) and AMP-activated protein kinase (AMPK) as well as the oncogenes Myc and hypoxia inducible factor 1α (HIF-1α)." (PMID 28574837, 2017). "Likewise, in other targeted therapies, cancer cells develop resistance mechanisms to overcome mTOR inhibition." (PMID 29104248, 2017). "The mTOR, a 289-KD serine/threonine protein kinase, plays a core role in multiple signaling pathways involving the mediation of cell growth, proliferation, apoptosis and autophagy, being considered a hotspot target for cancer therapy." (PMID 28061838, 2017).
cancer (continued). "Therefore, suppression of the mTOR pathway by an AMPK activator has been evaluated for therapeutics in cancers." (PMID 29228674, 2017). "Therefore, the metabolic context of mTOR inhibition in cancer cells is essential for understanding and improving its anti-tumor effects and toxicity profile." (PMID 28356082, 2017). "Indeed, a recent preclinical study has demonstrated that tubeimoside-1 can suppress cancer growth and angiogenesis by attenuating mTOR-AKT signaling in non-small cell lung cancer." (PMID 28961193, 2017). "mTOR signaling pathway has been suggested to play an critical role in cancer pathogenesis." (PMID 28406985, 2017). "Interestingly, in addition to genetic tools, our results showed that pharmacological mTOR and/or Mcl-1 inhibition using rapamycin and sorafenib respectively sensitized cancer cells to primarily tolerated doses of sunitinib." (PMID 29066973, 2017). "To date, numerous studies have investigated the association of genetic polymorphisms of pTEN/AKT/mTOR pathway genes including rs2295080, rs2536 of mTOR gene, rs2494750 and rs2494752 in the AKT1 gene, pTEN rs701848 with cancer susceptibility, however, the results were inconclusive." (PMID 29259266, 2017). "Tumor suppressor APC is lost in 85% of CRCs, leading to β-catenin stabilization, activation of Wnt targets such as c-Myc (Myc) and cyclin D1 and cancer initiation, which cooperates with hyperactivated RAS/RAF/ERK, and PI3K/AKT/mTOR signaling in cancer progression." (PMID 28030835, 2017). "PKM2 can also regulate cancer progression by activating mTOR or EGFR signalling pathway." (PMID 28373964, 2017). "Moreover, here we discuss the possibility of using compounds able to inhibit Deptor or to disrupt its interaction with mTOR as novel approaches for cancer therapy." (PMID 28086984, 2017). "In addition, we evaluated the relationship between MRS expression and the mTOR pathway, which plays a critical role in cancer growth and proliferation, to examine the relationship between tumor growth and MRS expression." (PMID 28679377, 2017). "Furthermore, besides the mTOR inhibitors, its upstream proteins regulating mTOR are also prevalent in cancer therapy." (PMID 28061838, 2017). "Indeed, one of these studies showed that dual inhibition of ULK1 and mTOR promoted cancer cell apoptotic death." (PMID 29233870, 2017). "Therefore, a systematically meta-analysis was performed to evaluate the association between the five SNPs (mTOR rs2295080 and rs2536, AKT1 rs2494750 and rs2494752, pTEN rs701848) and cancer risk by systematic review of the literature in 31 eligible studies." (PMID 29259266, 2017). "In some kinds of cancers, metformin could dampen tumorigenicity via inhibition of mTOR signaling pathway." (PMID 28406985, 2017). "In addition to HIF1-mediated effects, several HIF-independent pathways (such as mTOR) regulate the cancer cell metabolism." (PMID 28447025, 2017). "Two cancer pathways, mTOR signaling pathway and NOTCH pathway, were affected as well." (PMID 28567416, 2017). "However the prognostic value of mTOR signaling activation remained largely undefined in cancer patients." (PMID 28811537, 2017). "Activation of mTOR is vital for cancer cell cycle progression." (PMID 29137241, 2017). "When applied to BICA, both the mTOR inhibitor and anti-E-cadherin treatment could similarly inhibit cancer cells with high efficiencies." (PMID 28429794, 2017). "Moreover, we revealed that the anti-cancer effects of β-lapachone were mediated by the inactivation of the Akt/mTOR pathway." (PMID 28578385, 2017). "Contractions are a recurrent feature in cancer genomes with overactive mTOR and may predict sensitivity to DNA damaging chemotherapeutics." (PMID 28640831, 2017). "The PI3K/AKT/mTOR pathway is one of the major signaling pathways that regulate cell growth, proliferation, metabolism, and survival and is among the most commonly deregulated pathways in cancer, including in AML." (PMID 29254232, 2017).
cancer (continued). "The mTOR also interacts with rictor (rapamycin-insensitive companion of mTOR) and recent findings have suggested that the rapamycin-insensitive effect of mTOR on cell viability is up-regulated in many cancers." (PMID 29074560, 2017). "A master regulator of glucose metabolism in cancer cells is the PI3K/AKT/mTOR pathway." (PMID 29190880, 2017). "The metabolic consequences of decreased miR-33 and subsequent increase in PIM3 and PIM1, therefore, might also influence the cellular and systemic responses to mTOR inhibitors in cancer and other disease settings." (PMID 29170467, 2017). "Based on the results, we speculated that flaccidoxide-13-acetate may affect the ability of cancer cells to metastasize by inhibiting the FAK/PI3K/AKT/mTOR signaling pathway." (PMID 29280977, 2017). "Others suggested that combined inhibition of mTOR and MEK-ERK cascades could achieve better anti-cancer activity than mTOR inhibition alone." (PMID 28404914, 2017). "Recent studies have shown that dysregulation in mTOR signaling could lead to cancer and other pathologies." (PMID 28659828, 2017). "The PI3K/AKT/mechanistic target of rapamycin (mTOR) pathway promotes cell growth, proliferation, migration, and survival, and as such, aberrations within this signaling axis occur in the majority of breast and other cancers." (PMID 28423521, 2017). "Among EGFR downstream pathways, the AKT/mTOR pathway is upregulated in most cancers." (PMID 29234489, 2017). "Combining PI3K/mTOR and other pathway inhibitors or glucocorticoids may be an approach to overcome the therapeutic-resistance of certain cancers." (PMID 29100331, 2017). "These factors make the PI3K/Akt/mTOR pathway an attractive target for cancer therapy." (PMID 28108737, 2017). "These evidences point to the importance of mTOR pathway in cancer initiation and progression." (PMID 28822012, 2017). "We assessed the effects of mTOR inhibitor rapamycin and Akt inhibitor MK-2206, given as single drugs or in combination, on cell signaling, cell proliferation and apoptosis in a panel of cancer cell lines in vitro." (PMID 28991258, 2017). "In addition, cancer cells still maintain mTOR activation even though the activities of PI3K and Akt are suppressed." (PMID 28592260, 2017). "Thus, inhibition of the mTOR pathway represents a novel therapeutic strategy in the treatment of various cancers." (PMID 28330462, 2017). "Interestingly, RSV down-regulates PKM2 expression by inhibiting mTOR signaling, inducing a decrease in glucose uptake, lactate production, and reducing anabolic pathways in various cancer cell lines." (PMID 28272357, 2017). "In diverse cancer models, mTOR represents a central target for cancer therapy." (PMID 28362357, 2017). "In cancer tissues examined in this study, p-mTOR staining showed several characteristics." (PMID 28831205, 2017). "Three different types of chemical inhibitors of mTOR have been tested in various cancer models." (PMID 29104248, 2017). "In addition, activation of PI3K‐AKT‐mammalian target of rapamycin (mTOR) signaling is frequently observed in many cancer types as well." (PMID 28834289, 2017). "The main objective of this study is to build a refined computational model of mTOR regulation that could predict therapeutic targets to inhibit the progression of cancer." (PMID 28659828, 2017). "This could support an additional antiosteoclastic role for mTOR in the context of cancer-induced osteolysis." (PMID 28793923, 2017). "Inhibition of PI3K/mTOR, which mimics nutrient starvation, causes death of detached but not matrix-attached cancer cells." (PMID 28071763, 2017). "In conclusion, it is still uncertain whether conversion to mTOR inhibitors after cancer development will have any benefit in long-term patient and graft survival in kidney transplant recipients." (PMID 28160552, 2017).
cancer (continued). "Deregulation of the mTOR-signaling pathway (PIK3CA amplification/mutation, PTEN loss of function, Akt overexpression, and S6K1, 4EBP1 and eIF4E overexpression) is associated with several human disorders such as diabetes, obesity and cancer." (PMID 29137365, 2017). "Although clinically approved agents such as rapamycin, plays a therapeutic role in cancer therapy, mTOR inhibition has adverse effects in protein synthesis, cell proliferation, and immune function." (PMID 28670281, 2017). "Together, these processes allow cancer cells to escape mTOR-targeted therapies." (PMID 29263324, 2017). "Furthermore, the Atg7 protein was highly activated after the mTOR/p70S6K signaling pathway was triggered in DBT-treated cancer cells." (PMID 29179457, 2017). "The differential drug actions of RAD001 and BEZ235 suggest that it could be feasible to treat cancer cells with this combination, although they both target mTOR." (PMID 29290965, 2017). "PI3K-Akt-mTOR has been identified as a key signal pathway in regulating various aspects such as cancer cell proliferation, migration, apoptosis and autophagy, and in this study we did observed that R8 induced significant down-regulation of p-AKT and total-Akt than Sunitinib did." (PMID 29152075, 2017). "Thus, mTOR signaling is believed to be an essential component for tumor development and progression, and targeting mTOR is thought to be a promising strategy for cancer therapy." (PMID 29263324, 2017). "The mTOR is deregulated in several diseases such as cancer and diabetes." (PMID 29228561, 2017). "Of course, devotion to find novel pathways that regulate mTOR could be beneficial to predict new therapeutic targets for cancer." (PMID 28061838, 2017). "The data support dual targeting of PI3K/Akt/mTOR pathway in cancer treatment." (PMID 28991258, 2017). "However, under cellular stress conditions (such as hypoxia or cytotoxic chemotherapy), mTOR activity is disadvantageous for cancer cells and the suppression of mTOR activity by DDIT4 is important for tumor survival." (PMID 28484222, 2017). "Indeed, the pharmacological suppression of AKT reactivation by rapamycin, an allosteric mTOR inhibitor, has been shown to improve the anti-cancer efficacy of rapamycin." (PMID 29295560, 2017). "In addition to activation under hypoxic conditions, HIF1α can also be stabilized under a number of normoxic conditions, including as a result of activation of PI3K-Akt-mTOR signaling, Ras and Src, each of which can be upregulated in certain cancers." (PMID 28106780, 2017). "Hence, novel therapeutic strategies have to be designed to increase the efficacy of mTOR inhibitors in cancer." (PMID 29104248, 2017). "Our findings suggest that regulation of RNR might contribute to the promotion of tumorigenesis by mTOR and ‘addiction’ of cancer cells on mTOR signaling." (PMID 28507282, 2017). "Development of new PI3K/PTEN/Akt/mTOR inhibitors is of great clinical interest in cancer treatment." (PMID 29312623, 2017). "As pathway of PI3K/Akt/mTOR has prototypic functions in cellular proliferation, growth, differentiation, and survival, inhibition of these pathways would be a promising tool against cancer." (PMID 29311925, 2017). "mTOR is a kinase that senses the nutritional environment and is often over-active in cancer." (PMID 28640831, 2017). "However, little is known about the antitumor effect of telmisartan via AMPK/mTOR signaling in cancer cells." (PMID 28052030, 2017). "Rapamycin, an mTOR inhibitor, has been proposed as an anti-cancer drug." (PMID 29282029, 2017). "The mammalian target of rapamycin (mTOR) is a validated target in cancer treatment." (PMID 28054548, 2017).